RAD17 (RAD17 checkpoint clamp loader component)
Description:
Essential for sustained cell growth, maintenance of chromosomal stability, and ATR-dependent checkpoint activation upon DNA damage. Has a weak ATPase activity required for binding to chromatin. Participates in the recruitment of the 9-1-1 (RAD1-RAD9-HUS1) complex and RHNO1 onto chromatin, and in CHEK1 activation. Involved in homologous recombination by mediating recruitment of the MRN complex to DNA damage sites. May also serve as a sensor of DNA replication progression.
Synonyms: hRad17; R24L; Rad24; RAD17Sp; CCYC
Tractability: Small molecule: a structure with a bound ligand is known. PROTAC: ubiquitination databases record sites on it; its protein half-life has been measured.
Gene: Protein-coding gene on chromosome 5 (69,369,293 to 69,414,806, forward strand). Ensembl gene ENSG00000152942.
Subcellular location: Nucleus; Chromosome
Subcellular location (Human Protein Atlas): Nucleoplasm
Pathways (Reactome):
DNA Repair: HDR through Single Strand Annealing (SSA); Presynaptic phase of homologous DNA pairing and strand exchange; Processing of DNA double-strand break ends
Cell Cycle: Activation of ATR in response to replication stress; G2/M DNA damage checkpoint
Disease: Impaired BRCA2 binding to RAD51
Gene Ontology:
Molecular function: chromatin-protein adaptor activity; protein binding; DNA clamp loader activity
Biological process: DNA damage response; mitotic intra-S DNA damage checkpoint signaling; negative regulation of DNA replication; protein localization to site of double-strand break; regulation of phosphorylation; DNA repair; DNA replication checkpoint signaling; mitotic DNA replication checkpoint signaling; chromatin organization; DNA damage checkpoint signaling
Cellular component: chromosome; chromosome, telomeric region; nucleolus; nucleoplasm; nucleus; Rad17 RFC-like complex; site of double-strand break; chromatin; chromosome, telomeric repeat region
Genetic constraint (gnomAD): Loss-of-function variants: 27 observed, 70.63 expected, observed/expected ratio (o/e) 0.38, 90% interval 0.28 to 0.53. The upper end of that interval is the gene's LOEUF score, 0.53, which puts it in group 2 of 6, group 1 being the genes least tolerant of losing a copy. Missense variants: 632 observed, 732.92 expected, observed/expected ratio (o/e) 0.86, 90% interval 0.81 to 0.92. Synonymous variants: 239 observed, 245.97 expected, observed/expected ratio (o/e) 0.97, 90% interval 0.87 to 1.08.
Homologues: Orthologues: chimpanzee RAD17 (99% identical), macaque RAD17 (97% identical), pig RAD17 (89% identical), dog RAD17 (88% identical), guinea pig RAD17 (82% identical), mouse Rad17 (81% identical), rat Rad17 (80% identical), rabbit RAD17 (77% identical), tropical clawed frog rad17 (58% identical), zebrafish rad17 (49% identical), Drosophila melanogaster Rad17 (24% identical), Caenorhabditis elegans hpr-17 (23% identical).
Diseases named in the same sentence as RAD17 in open-access papers:
RAD17 is named in the same sentence as 36 diseases in open-access papers, as found by Europe PMC text mining. Sharing a sentence is not in itself a finding about the gene and the disease. The quoted sentences say what the papers report.
breast carcinoma (8 papers, 2011 to 2024). "In some breast cancer patients, loss of RAD17, RAD50, and RAP80 s genes which participate into the BRCA1‐dependent DNA repair was associated with significantly increased genomic instability and poor patient survival." (PMID 26663100, 2016). "Further molecular genetic analyses are required to validate the effect of the c.1605 + 2T > A variant, and warrant further exploration of RAD17 and DDR genes in additional familial pancreatic and breast cancer cohorts." (PMID 38872153, 2024). "One previous study found that breast cancer cells harbor higher RAD17 levels and a slower rate of Cdh1/APC-mediated RAD17 protein turnover compared with breast epithelial cells." (PMID 35844787, 2022). "Knockdown of RAD17 sensitizes breast cancer cells to cisplatin, which is consistent with our results of ATR inhibition reversing topotecan resistance." (PMID 35844787, 2022). "Previous studies have reported that human Rad17 is overexpressed in diverse cancers, including colon carcinoma, breast cancer, pancreatic cancer, gastric cancer and non‐small‐cell lung cancer." (PMID 31845510, 2020). "Previous studies have reported that Rad17 expression is elevated in colon carcinoma, breast cancer, pancreatic cancer, gastric cancer and non‐small‐cell lung cancer and is correlated with tumour cell onset and progression." (PMID 31845510, 2020). "Therefore, RAD17 mutations are an interesting and potentially actionable addition to previously identified genes in the DNA damage response (DDR) pathway in pancreatic cancer and breast cancer." (PMID 38872153, 2024). "Finally, we assessed the potential correlation between RAD17 and BRCA1 DNA repair genes expression and clinical outcome in a cohort of sporadic basal-like breast carcinomas (BLCs)." (PMID 25650659, 2015).
head and neck squamous cell carcinoma (6 papers, 2015 to 2025). A squamous cell carcinoma that arises from any of the following anatomic sites: lip and oral cavity, nasal cavity, paranasal sinuses, pharynx, larynx, and salivary glands. "Experiments verified that the miR-205-5p/BRCA1/RAD17 axis increased the level of γ-H2AX and made DNA repair inefficient in head and neck squamous cell carcinomas in vivo and in vitro, revealed that miR-205-5p/BRCA1/RAD17 axis had the potential to be a therapeutic target for cancer." (PMID 35591858, 2022). "We initially evaluated whether miR-205-5p, a microRNA (miRNA) highly expressed in head and neck squamous cell carcinoma (HNSCC), targeted BRCA1 and RAD17 expression." (PMID 31514456, 2019).
lung carcinoma (5 papers, 2011 to 2024). "Increased levels of RAD17 are linked with breast and lung carcinomas." (PMID 30379886, 2018). "However, it still may be upregulated in thyroid and uterine cancer (PDE4DIP) and lung cancer (RAD17)." (PMID 38544823, 2024). "In lung cancer, the interaction of IQGAP3 with DNA repair protein Rad17 was essential for Rad17 expression and foci formation, the Mre11-Nbs1-Rad50 complex formation, and ATM/Chk2 and ATR/Chk1 pathways activation." (PMID 36275458, 2022). "In lung cancer, IQGAP3 directly bind repair protein Rad17 to regulate its expression and localization at the DNA damage site, so as to promote DNA repair." (PMID 36275458, 2022).
pancreatic cancer (4 papers, 2020 to 2024). "We identified RAD17 as a novel candidate cancer predisposition gene in a breast and pancreatic cancer family." (PMID 38872153, 2024). "Within families with breast and pancreatic cancer, we identified RAD17 as a novel candidate predisposition gene." (PMID 38872153, 2024). "Therefore, further germline testing of pancreatic cancer patients for DDR genes, including RAD17, may further establish their role in cancer predisposition." (PMID 38872153, 2024).
colon carcinoma (3 papers, 2011 to 2020). "Two of the three cell lines most sensitive to RAD17 knockdown were GP2D and LS411N, both colon cancer cell lines harboring CHEK1 mutation." (PMID 26437225, 2015).
lymphoma (3 papers, 2015 to 2022). A malignant (clonal) proliferation of B- lymphocytes or T- lymphocytes which involves the lymph nodes, bone marrow and/or extranodal sites. "An RNAi screen indicated that Rad17 acts as a haploinsufficient tumour suppressor in a mouse lymphoma model." (PMID 29089486, 2017). "This experiment, originally performed before our RNA Seq and proteomic analysis of reimplanted Eμ-Myc lymphomas was completed, revealed lower levels of Claspin mRNA and protein expression in primary RelA T505A Eμ-Myc lymphomas, while ATR, CHK1, ATRIP, RAD17 and TOPBP1 were unaffected." (PMID 36240065, 2022). "Given prior reports of synergy between CHEK1 and WEE1 inhibitors in lymphoma, leukemia, and solid tumor cell lines, we suspected that simultaneous inhibition of CHEK1 and WEE1 might further magnify the synthetic lethal effect with RAD17 knockdown." (PMID 26437225, 2015).
head and neck cancer (2 papers, 2011 to 2019). A primary or metastatic malignant neoplasm affecting the head and neck. "Altogether, these findings strongly suggest that miR-205-5p significantly impacts the DNA repair ability of head and neck cancer cells through the repression of BRCA1 and RAD17 gene expression." (PMID 31514456, 2019).
adenoid cystic carcinoma (1 paper, 2015). A malignant tumor arising from the epithelial cells. "RAD17 is frequently deleted in adenoid cystic carcinoma (13.3%) and prostate adenocarcinoma (13.1%, 5.9%) and frequently mutated in pancreatic adenocarcinoma (7.0%) and stomach adenocarcinoma (4.5%)." (PMID 26437225, 2015).
colorectal cancer (1 paper, 2024). A primary or metastatic malignant neoplasm that affects the colon or rectum. "PDE4DIP and RAD17 both do not play a major role in causing colorectal cancer, as observed and corroborated by gene expression profiling studies." (PMID 38544823, 2024).
dysferlinopathy (1 paper, 2023). "Analysis of muscle transcripts from patients with dysferlinopathy identified 6 downregulated DEGs (RFC4, RFC5, ATAD5, TP53BP1, WDR48, and RAD17) related to the cellular response to DNA damage stimulus." (PMID 38125829, 2023).
glioma (1 paper, 2020). A benign or malignant brain and spinal cord tumor that arises from glial cells (astrocytes, oligodendrocytes, ependymal cells). "Regarding major nodes in the DNA repair network, ERCC1, FANCD2, and RAD17 have been associated with therapy resistance in gliomas and other tumor types." (PMID 31969990, 2020).
viral infection (1 paper, 2020). "RNAseq and protein expression analysis ofDDB2,RAD17,PRKDC,PCNA and other ATR pathway markers of infected cells accompanied by time course studies of nascent double stranded chromosomal breaks (i.e. H2AX antibody staining due to viral infection) would provide such evidence." (PMID 33299552, 2020).
cancer (13 papers, 2011 to 2025). A tumor composed of atypical neoplastic, often pleomorphic cells that invade other tissues. "Taken together, the combination of a loss of function variant and its absence from controls, qualifies RAD17 as a cancer predisposition gene." (PMID 38872153, 2024). "By contrast, somatic mutations in RAD17 have been found in several types of cancer including PC (7%), together with features that support a tumor suppressor role such as LOH and biallelic loss." (PMID 38872153, 2024). "A reduction or loss of RAD17 protein may therefore lead to an increased risk of cancer and genomic instability." (PMID 38872153, 2024). "To assess whether there is evidence of interaction between RAD17 and the checkpoint kinases in primary human tumors, we examined somatic mutation, copy number variation, and mRNA expression data from ~8000 biopsy specimens spanning multiple cancer types in TCGA." (PMID 26437225, 2015). "Query of the cBioPortal for Cancer Genomics indicated that RAD17 is the most frequently altered of the four TSGs with a pan-cancer incidence of 1.9%." (PMID 26437225, 2015). "Furthermore, miR-506-3p has been identified to target RAD17, a key component of the HR pathway, thereby diminishing cancer cells' ability to sense DNA damage in OC." (PMID 40248198, 2025). "In this scenario, we highlighted the pivotal role in DNA damage signaling of RAD17 protein and recent literature demonstrated that RAD17 is a conserved key node for synthetic lethal interactions relevant for cancer therapy and specifically with cell cycle checkpoint kinases." (PMID 35924161, 2022). "To determine if the interaction between CHEK1/2 and RAD17 was also present across a diverse set of cancer cell lines we analyzed data generated from Project Achilles, a cancer cell-line based functional genomic screen in which over 11,000 genes were knocked down with shRNA in 102 cell lines." (PMID 26437225, 2015). "Genes LGALS8, PDE4DIP, RAD17, ELN, MUC4 and SEMA4D had a mid-range expression in both cancer types, while OPRM1 and ADRA1 were the least expressed, thereby corroborating the results from our box plot and survival analysis." (PMID 38544823, 2024). "Additional evidence for this interaction was found in a large-scale functional shRNA screen of over 100 genotyped cancer cell lines, in which CHEK1/2 mutant cell lines were unexpectedly sensitive to RAD17 knockdown." (PMID 26437225, 2015). "In contrast, the expression of the checkpoint sensors ATR, RAD9, and RAD17 was only modestly increased in cancer samples relative to normal tissues, and did not correlate with the downstream components of the pathway." (PMID 30796221, 2019). "This supposition is supported by the fact that (excluding hyper-mutated tumors) there are no occurrences of tumors with mutations in both RAD17 and either CHEK1, CHEK2 and WEE1 across all cancer types in TCGA." (PMID 26437225, 2015). "The expression levels of LIAS had a positive correlation with the expression levels of CTD-2366F13.1 (R = 0.47, p < 0.001), RAD17 (R = 0.48, p < 0.001), OCIAD1 (R = 0.49, p < 0.001), PACRGL (R = 0.49, p < 0.001), MRPS27 (R = 0.49, p < 0.001), and THAP9 (R = 0.49, p < 0.001) in pan-cancer." (PMID 35982953, 2022). "This analysis revealed that Claspin, Timeless, and CHK1 are overexpressed in a coordinated manner in these three cancers whereas the checkpoint sensors ATR, RAD17, and RAD9 are not." (PMID 30796221, 2019). "We found that unlike the checkpoint sensors ATR, RAD9, and RAD17, the downstream components of the ATR pathway Claspin, Timeless, and CHK1 show a correlated overexpression in cancer cells." (PMID 30796221, 2019).
tumor (13 papers, 2011 to 2024). "We postulate that the RAD17 splice variant leads to a loss of function of a protein involved in the DNA damage repair, hence functioning a tumor suppressor gene." (PMID 38872153, 2024). "BRCA1 and RAD17 mutations are rarely detected in sporadic tumours." (PMID 25650659, 2015). "All BRCA1, RAD17 and Chk1 mutations are rarely detected in sporadic tumours." (PMID 25650659, 2015). "Given the role of DNA damage checkpoints in homologous recombination, tumor sensitivity to PARP inhibition and platinum-based chemotherapy should be investigated in relation to germline mutations in RAD17." (PMID 38872153, 2024). "Conversely, miR-205-5p downregulation increased BRCA1 and RAD17 messenger RNA (mRNA) levels, leading to a reduction in in vivo tumor growth." (PMID 31514456, 2019). "Clinically, the low expression of the BRCA1/RAD17 signature in HNSCC tumor samples was found to be significantly anti-correlated with miR-205-5p expression and associated with high recurrence." (PMID 31514456, 2019). "While the reduction of BRCA1 and RAD17 expression in sporadic cancers is well established, the molecular mechanisms by which their expression is downregulated in tumour cells are still unclear." (PMID 25650659, 2015). "Furthermore, through gene expression profiling interactive analysis (GEPIA), we found that the gene expression of USF2 was positively related to RAD17 or NELFA in multiple tumours." (PMID 31845510, 2020). "To determine the correlation between the expression of DNA repair genes and the inhibition of tumor growth by miR-205-5p injection, we stained tumoral tissues of the sacrificed mice for BRCA1 and RAD17 expression." (PMID 31514456, 2019). "Several of these genes (including MGMT, RAD17, and USP44) show prior evidence of a tumour suppressive function." (PMID 29089486, 2017). "Consistently, we found a significant reduction in tumor growth and increased levels of BRCA1 and RAD17 in xenografted tumors arising from the HNSCC CAL27 cell line, orthotopically and intrascapularly injected in immunocompromised mice and subsequently treated with miR-205-5p synthetic inhibitors." (PMID 31514456, 2019). "Importantly, we also found that in low-grade NSCLC, increased expression of Claspin, Timeless, and CHK1 (but not ATR, RAD9, and RAD17), correlates with the aggressiveness of the tumor." (PMID 30796221, 2019).
infection (1 paper, 2025). The state of being infected such as from the introduction of a foreign agent such as serum, vaccine, antigenic substance or organism. "The observed upregulation of MRNIP, RAD17, and SIRT1 in the Ml group indicates an active DDR alongside mechanisms that preserve genomic integrity and immune equilibrium during infection." (PMID 41333726, 2025).
RAD17 also shares sentences with these, for which no sentence is quoted: ovarian carcinoma (3 papers); glioblastoma (2); melanoma (2); non-small cell lung carcinoma (2); benign ovarian tumors (1); breast tumors (1); cervical adenocarcinoma (1); colorectal adenocarcinoma (1); epilepsies (1); gastric cancer (1); head and neck tumors (1); leukemia (1); lymph node metastasis (1); mucinous ovarian cancer (1); mucinous tumors (1); pancreatic adenocarcinoma (1); prostate adenocarcinoma (1); serous ovarian cancer (1); stomach adenocarcinoma (1); triple-negative breast carcinoma (1); uterine cancer (1).